VEGFA (vascular endothelial growth factor A)
Diseases named in the same sentence as VEGFA in open-access papers (continued):
Sharing a sentence is not in itself a finding about the gene and the disease.
tumor (continued). "Vascular endothelial growth factor-A (VEGFA) may be a viable target gene of miR-125a-5p, where it could bind to its receptor VEGFR2 and be strongly related to tumor growth." (PMID 37587156, 2023). "Recently, a single-cell study on MCs in pan-cancer classified tumor MCs into two subtypes: anti-tumorigenic MCs, which are characterized by a high TNF/VEGFA expression ratio, and pro-tumorigenic MCs, which are characterized by a low TNF/VEGFA expression ratio." (PMID 38031173, 2023). "In addition, we used other algorithms to evaluate the relationship between VEGFA expression and the infiltration of immune cells, including CD8+ T cells, CD4+ T cells and regulatory T cells, in various tumours." (PMID 36729917, 2023). "By contrast, only 7.14% of patients with lower PFS presented high expression scores of VEGFA, while the large majority (71.43%) exhibited no overexpression of the protein in the tumor." (PMID 37893095, 2023). "Moreover, tumor‐derived CXCL1 and CXCL8 increased CXCR2, ERK and JNK pathways‐dependent production of VEGFA and MMP9 in neutrophils, which led to lymphangiogenesis." (PMID 36670069, 2023). "This may indicate that control of tumor growth is dominated by targeted therapies and that a constant influence of the BRAF/VEGFA targeting on TME should be required to exploit the best efficacy of anti‐PD‐1 treatment." (PMID 37183363, 2023). "We analysed the expression of VEGFA mRNA in different human tumour tissues and corresponding normal tissues from the TCGA database and GEO database." (PMID 36729917, 2023). "In the 18 samples that did not have an altered VEGFA gene copy number, induction of the protein in tumor cells was of varying degrees: high overexpression in 6 cases (score 100–180), moderate overexpression in 6 (score 10–90), and absent in 5 patients." (PMID 37893095, 2023). "IHC results manifested that Ki67 and VEGFA expression in tumor tissues was decreased via ELF5 but not ELF-ΔSET overexpression." (PMID 37980532, 2023). "Moreover, the expression of VEGFA was significantly higher in the TN, whereas the IFN‐stimulated gene (e.g., ISG15) was higher in the tumour edge." (PMID 37491740, 2023). "Nevertheless, we observed the sequential use of anti‐PD‐1 antibody, after 2 weeks of BRAF/VEGFA targeting, failed to improve tumor control and the tumors rapidly relapsed." (PMID 37183363, 2023). "When the VEGFA/VEGFR pathway is blocked, other pro-angiogenic factors restore tumor angiogenesis." (PMID 37508458, 2023). "VEGFA was reported to enhance OSCC cell proliferation and tumor initiation." (PMID 37234708, 2023). "Interestingly, however, the expression of two potentially tumor-promoting genes, OSM and VEGFA, was upregulated in both the TGF-β1- and M4 TCM-treated dHL-60 cells." (PMID 37682817, 2023). "Three pathogenic variants were identified: c.1320+1G>A in the CDH1 gene and c.27_28insCCCAGCCCCAGCTACCA (p.Ala9fs) of the VEGFA gene were found only in the tumor tissue, whereas c.G1874C (p.Cys625Ser) in the FANCA gene was found in both the tumor and normal tissue." (PMID 36833207, 2023). "Thus, the key feature of PTX-resistant cells was the overexpression of pro-angiogenic factors such as VEGFA, VEGFC, and Ang2, known to support tumor cell growth." (PMID 36874116, 2023). "Given our above results showing that DHA regulates LOXL2/VEGFA expression and affects the fatty acid oxidation program, we presume that DHA may exert a synergistic anti-tumor effect with antiangiogenic drugs." (PMID 37056396, 2023). "Furthermore, we explored the TMN plot to compare VEGFA, CTNNB1, MMP7, and CD44 oncogenes in tumor and metastatic CRC samples from RNA sequencing data (RNAseq)." (PMID 36672201, 2023). "Meanwhile, the results of in vitro experiments further showed that LW6 could effectively inhibit tumor angiogenesis by inhibiting the expressions of HIF-1α and VEGFA." (PMID 37239383, 2023).
tumor (continued). "Consistent with our hypothesis, the Aspiletreins bound to the targets with high affinity and likely inhibited the tumor-promoting functions of STAT3, VEGFA, HSP90AA1, and FGF2 or enhanced tumor-suppressing activity of IL2, or both." (PMID 36707691, 2023). "As shown in, we confirmed that miRNA-383-5p transfection alone indeed inhibited the expression of VEGFA/VEGFR2, whereas the expression of VEGFA/VEGFR2, in the miRNA-383-5p + VEGFA pcDNA group, was not different from the tumor control group." (PMID 37592783, 2023). "We observed that dual therapy induced a statistically significant increment of tumor‐infiltrating M‐MDSCs compared with the control group, while BRAFi and anti‐m‐VEGFA single therapy did not alter the presence of M‐MDSCs." (PMID 37183363, 2023). "ITGA5/VEGFA coexpression was observed in a tumor cell subpopulation and the decreased endothelial angiogenesis by downregulating ITGA5 could be reversed by VEGFA." (PMID 36999964, 2023). "Both in vitro and in vivo studies confirmed that EVs rich in these miRs inhibit cell proliferation and migration but also induce apoptosis by downregulation of several angiogenesis-related factors (such as VEGFA, MMP-9 and ANGPT) and inhibit micro-vascular formation in OSCC tumours." (PMID 37242569, 2023). "The same group demonstrated that miR-145-5p tumor suppressive function was also performed through other targets, namely NRAS and VEGFA (vascular endothelial growth factor A), thus impairing invasion and angiogenesis in vitro, and also tumor growth and angiogenesis in vivo." (PMID 36765733, 2023). "Moreover, FABP5 promotes tumor angiogenesis and activates the IL6/STAT3/VEGFA pathway in HCC, as evidenced by studies." (PMID 37576389, 2023). "Then, to investigate whether macrophages were recruited in TME by A549S25E cells showing high expression of VEGFA and IL1A, mouse tumor tissues were stained with specific macrophage antibodies for TAM marker CD163 and pan-macrophage marker CD68." (PMID 37968723, 2023). "Moreover, the EMT tumour cells can modulate the tumour microenvironment, and it is reported that the upregulation of SLUG increases the downstream expression of VEGFA and CXCL12 and promotes the angiogenesis." (PMID 37867401, 2023). "Tumor proliferation and metastasis are often accompanied by increased vascular density, and VEGF promotes tumor neovascularization by secreting various pro-angiogenic factors, including VEGFA." (PMID 37614510, 2023). "Moreover, a directly proportional correlation was observed between SHH and VEGFA immunoreactivity in TNM 3 + 4 and Fuhrman/ISUP/WHO 3 + 4 tumor tissues as well as in samples of patients with shorter survival." (PMID 37964226, 2023). "Downregulation of ITGA5 in tumor cells significantly decreased p‐AKT and VEGFA levels." (PMID 36999964, 2023). "Tumor-cell-specific deMuts included many COSMIC genes, such as VEGFA, NEAT1, MALAT1, HILPDA, etc.." (PMID 37433798, 2023). "ESM1 can activate the downstream MAPK/ERK signaling pathway by binding to the c-Met membrane receptor of vascular endothelial cells and can promote the expression of HIF1α, VEGFA, MMP9, and other pro-angiogenic factors, thereby promoting tumor angiogenesis and peritoneal metastasis." (PMID 38201620, 2023). "VEGFA, also called vascular endothelial growth factor-A, is not the only, major factor driving tumor vascular bed dilation." (PMID 35069936, 2022). "The expression levels of CCND1, VEGFA, AURKB, HDAC1, HSP90AA1, and HSP90AB1 were positively correlated with immune cell infiltration levels, whereas the expression levels of SIRT2 and CASP9 were negatively correlated with the tumor purity of BRCA." (PMID 35845599, 2022). "Also, the angiogenesis-related molecules including PDGFB, VEGF, VEGFA, and PDGFRB were significantly downregulated by MTE, especially by high-dose MTE in the HCC-PDX tumor." (PMID 35847002, 2022).
tumor (continued). "A study has revealed that NCBP2-AS2 was overexpressed in hypoxic-cancer-associated fibroblasts, and it can promote the secretion of pro-angiogenic factor VEGFA, consequently reducing VEGF/VEGFR downstream signaling, which leads to tumor metastasis and reduces the efficacy of therapy." (PMID 36010268, 2022). "In this context, CAFs often have upregulated expression of hypoxia-induced angiogenesis regulator (HIAR), which can increase CAF motility and secretion of vascular endothelial growth factor A (VEGFA) and further promote angiogenesis, thereby facilitating oxygenation and nutrient flow of the tumor." (PMID 35488263, 2022). "Such specificity may offer an enhanced therapeutic window that enables suppression of the IPRES processes in the tumor microenvironment while sparing the normal homeostatic functions of TGF-β and VEGFA in healthy tissues." (PMID 35577211, 2022). "Then, we picked out 8 HAIRGs (VEGFA, CTNNB1, PPARG, HSP90AA1, HMOX1, LGALS3, SPP1, and RAC1) from the 17 HAIRG model through the LASSO Cox regression, upregulated genes accounted for 7/8 in tumor tissue, which was shown by a heat map." (PMID 35069936, 2022). "Different types of signaling molecules so far have identified as inducers of tumor angiogenesis, among which the vascular endothelial growth factor-A (VEGF-A), also referred to as VEGF, and its receptor VEGF receptor-2 (VEGFR-2) are major activators of tumor angiogenesis." (PMID 34983556, 2022). "Moreover, expression of both VEGFA and VEGFR2 proteins was obviously decreased in tumor tissues of the swimming group (P < 0.05; vs control group)." (PMID 35291563, 2022). "They showed that four tumor-specific mRNA (ALOX5, RBL2, VEGFA, TLK2) present in EVs (defined as present in tumor-derived-, urine- and plasma-EVs, but absent in tumor-adjacent tissue EVs) may be used as RCC biomarkers in the future." (PMID 35629194, 2022). "Furthermore, VEGFD inhibits LUAD angiogenesis by competing with VEGFA to bind to VEGFR2 in LUAD, and it also induces tumor apoptosis, which is our next research scope." (PMID 35941690, 2022). "An antagonist peptide of VEGFA/VEGFB, referred to as VGB3, can recognize and neutralize both VEGFR1 and VEGFR2 on the endothelial and tumoral cells, thereby inhibits angiogenesis and tumor growth." (PMID 34983556, 2022). "Another tumor secretome released in an autophagy-dependent manner includes growth factors (TGF-β1, b-FGF), extracellular matrix proteins (MMP2, MMP9) and the angiogenesis stimulant (VEGFA)." (PMID 36160153, 2022). "Furthermore, we also confirmed the regulatory effects of cNFIB on CCND1, MMP1, VEGFA, and FOS expression, the key downstream targets of ERK signaling responsible for tumor proliferation and metastasis." (PMID 35039066, 2022). "In contrast, no beneficial phenomenon was observed in tumor-bearing mice without VEGFA overexpression." (PMID 35844616, 2022). "Indeed, VEGFA can induce the activation of the master regulator of T cell exhaustion, TOX, as well as the expression of the PD-1 checkpoint in tumor-reactive, CD8+ T cells." (PMID 35577211, 2022). "Mechanically, circPOSTN exerted its tumor-promoting effect by acting as a ceRNA to inhibit the miR-219a-2-3p/STC1 axis, upregulating the expression of oncogene STC1, and therefore facilitated VEGFA secretion." (PMID 35927233, 2022). "Others orthotopic murine model once again showed that in animals treated with either DC101, bevacizumab or VEGF‐Trap (a decoy molecule trapping VEGFA) confirmed that presence of nonangiogenic cancer cells can lead to tumor progression." (PMID 33295149, 2022). "As such, the combination of anti-VEGFA and ICB is being tested in a multiple tumor histologies." (PMID 35577211, 2022). "Additionally, LINC00022 knockdown decreased the protein expression levels of c-Myc, MMP2, and VEGFA in tumor tissues and increased cleaved caspase 3 levels, whereas LINC00022 overexpression increased c-Myc, MMP2, and VEGFA protein levels." (PMID 35468741, 2022).
tumor (continued). "We performed Masson’s trichrome staining to observe tumor fibrosis and immunohistochemistry (IHC) staining to measure the expressions of PLGF, VEGFA, and their receptors (NRP1, VEGFR1, VEGFR2) using tissues derived from 10 PDAC patients with poor prognosis and 10 PDAC patients with good prognosis." (PMID 36272973, 2022). "This tumor-mediated VWF secretion is via tumor secretomes acting on neighboring endothelial cells, including inflammatory cytokines, matrix metalloproteinases, and pro-angiogenic mediators such as VEGF-A (vascular endothelial growth factor A)." (PMID 35327035, 2022). "IHC results also validated that linc00958 downregulation could inhibit the tumor microvessel density marker CD34 and VEGFA in tumors, supporting that the knockdown of linc00958 inhibited the angiogenesis in xenograft model." (PMID 36056431, 2022). "Consequently, this axis activates VEGFA/VEGFR2 signaling pathway, resulting in angiogenesis and resistance of tumor cells to sunitinib in ccRCC." (PMID 35562342, 2022). "Gene Ontology (GO) and Kyoto Encyclopedia of Genes and Genomes (KEGG) analysis of SLC25A13 coexpressed genes showed that these genes are enriched in ATPase activity, cell cycle, mTOR, and VEGFA-VEGFR2 signaling pathways, which were relevant to tumor development and angiogenesis." (PMID 35607442, 2022). "In CC mice with knockdown of linc00958, the tumor microvessel density biomarker CD34 and VEGFA were significantly inhibited, revealing that knockdown of linc00958 could attenuate tumor angiogenesis." (PMID 36056431, 2022). "Besides, bevacizumab is known as a world-famous monoclonal antibody targeting vascular endothelial growth factor A (VEGF-A), which is crucial for tumor growth and TNBC metastasis." (PMID 36188535, 2022). "Moreover, suppression of PELP1 reduced tumor growth and angiogenesis in vivo accompanied by inactivation of STAT3/VEGFA pathway." (PMID 35053547, 2022). "In addition, immunohistochemical staining revealed knockdown circAFAP1 decreased the expression of VEGFA, p-erk, ki-6,7, and blood vessel marker CD31 in tumor tissues which were restored by miR-374b-3p suppression or VEGFA upregulation." (PMID 35173146, 2022). "Vascular endothelial growth factor A (VEGFA), a key player in promoting the proliferation and migration of endothelial cells and improving vascular permeability has shown higher mRNA and protein levels in HCC tumor cells than those in paracarcinoma tissue." (PMID 36624801, 2022). "Specifically, IL-6 is released by cells in the tumor microenvironment and increases the production and subsequent release of VEGF into the environment via the IL-6/STAT3/VEGFA pathway, promoting endothelial cell activation and the subsequent formation of tubular structures." (PMID 36555614, 2022). "It has been reported that IRES-A could initiate VEGFA translation at AUG and synthesize a secreted form of VEGFA, which is crucial for the tumor angiogenesis." (PMID 35054929, 2022). "Besides, TANs also promote tumor angiogenesis by releasing the pro-angiogenic factors BV8, S100A8/9, and MMPs that activate VEGFA in the extracellular matrix." (PMID 35585567, 2022). "The Insulin signaling pathway in group 5 was found to mainly lead to activation of genes involved MAPK signaling and this trend converges with hypoxia signaling input, both leading to the production of VEGFB, VEGFA, PGF, growth factors known to be involved in angiogenesis and tumor invasion." (PMID 35568708, 2022). "VEGFA plays an important role in the formation of VM; it can bind and activate its tyrosine kinase receptors, VEGFR1 and VEGFR2, to influence VM formation in different tumor cell types." (PMID 35595748, 2022). "In the intraperitoneal metastatic microenvironment, CAFs govern the metastatic cascade, including the adhesion, proliferation, invasion, and colonization of metastatic sites via increasing production of several molecules (CXCL12, IL-6, VEGFA, TGF-α, and β, FGF-1) within the tumor microenvironment." (PMID 35216340, 2022).
tumor (continued). "Caffeic acid also increased mRNA levels of TIMP-1 and TIMP2 (tissue inhibitors of metalloproteinases 1 and 2), and decreased mRNA levels of VEGFA (vascular endothelial growth factor A), metalloproteinases MMP-2, and MMP-9, essential for aggressive tumor growth and metastases." (PMID 36614030, 2022). "In our preliminary study, we depleted macrophages in SCC models and found downregulated TGF-β1 and VEGFA in tumor cells, demonstrating that TGF-β1 reduction could be sufficient to reduce VEGFA-dependent angiogenesis after TAM ablation." (PMID 35327584, 2022). "Hence, we concluded that in NPC tumors, LBH-mediated inactivation of CRYAB and VEGFA in HUVECs can be induced by LBH+ NPC exosome in a paracrine manner, thus impairing NPC tumor angiogenesis." (PMID 34975330, 2022). "The expressions of VEGFA and CSPG4 genes and also human β-actin as the reference gene were examined using the quantitative real-time polymerase chain reaction method in the formalin-fixed paraffin-embedded tumor tissues." (PMID 36422502, 2022). "Based on our RNA-seq data analysis, EphA2 and VEGFA were enriched in growth and vasculature development in HCT116 cells; therefore, we evaluated the tumor‐promoting ability of METTL3 and its target genes, EphA2 and VEGFA, by upregulating EphA2 and VEGFA using a GV230 overexpression vector." (PMID 35595748, 2022). "While we did not observe a difference in VEGFA levels between the DSG2‐high and DSG2‐low patients in the non‐MS cohort, other genes associated with tumour vascularization (e.g. SOX4 and SOX2) were co‐expressed with DSG2." (PMID 34245117, 2022). "Importantly, integrin α6 has been documented in vascular endothelial growth factor-A (VEGF-A) and fibroblast growth factor-2-driven angiogenesis, promoting tumor growth in vivo and in vitro." (PMID 35494001, 2022). "However, it is worth noting that compared with the Saline group, the expression level of VEGFA protein in the CON group was significantly increased (P<0.05), which is beneficial to tumor growth and metastasis." (PMID 35371324, 2022). "Additionally, linc00941 interacts with miR-877-3p to regulate VEGFA, accelerating NSCLC angiogenesis and tumor progression." (PMID 35918758, 2022). "In previous studies, tumor-related genes TNF-α, VEGFA, and c-Myc were also regulated by HDAC1." (PMID 35053925, 2022). "The expression of TNF, VEGFA, and IL6 in the transplanted tumor cells could be regulated by using Celastrol, and the expression trends were consistent with the in vitro model." (PMID 36506508, 2022). "It was revealed that in GC tumor tissues and GC cells, in contrast with the Vector group, CALM2 overexpression greatly facilitated JAK2 and STAT3 phosphorylation and elevated the protein expressions of HIF-1 and VEGFA." (PMID 34604066, 2021). "Thus, not only HIF1A, but also VEGFA, SLC2A1, and CA9 allow the tumor cells to survive in hypoxic environments and are well-established markers of cellular hypoxia." (PMID 33810575, 2021). "Tumor cells attempt to kidnap VEGF-A165a and expel VEGFA-165b so that they could promote cancer development." (PMID 34544400, 2021). "Within the TME, TAMs have been shown to migrate deep into tumor hypoxic regions where they can support tumor cell migration and invasion via ECM remodeling by the upregulation of MMP-2, -7, and -9, and stimulate angiogenesis through enhanced VEGFA production." (PMID 34884995, 2021). "Results confirmed BAF312@cRGD-CaP-NP could dramatically inhibit tumor growth and angiogenesis in vitro and in MDA-MB-231 tumor-bearing mice via downregulating the S1PR1/P-STAT3/VEGFA axis." (PMID 34059068, 2021). "HIF-1α, VEGFA, and TGF-β1 are important factors for tumor angiogenesis." (PMID 34769497, 2021).